TTLL6 (tubulin tyrosine ligase like 6)
Description:
Polyglutamylase which modifies both tubulin and non-tubulin proteins, generating alpha-linked polyglutamate side chains on the gamma-carboxyl group of specific glutamate residues of target proteins. Preferentially mediates ATP-dependent long polyglutamate chain elongation over the initiation step of the polyglutamylation reaction. Preferentially modifies the alpha-tubulin tail over a beta-tail. Promotes tubulin polyglutamylation which stimulates spastin/SPAST-mediated microtubule severing, thereby regulating microtubule functions. Mediates microtubule polyglutamylation in primary cilia axoneme, which is important for ciliary structural formation and motility. Mediates microtubule polyglutamylation in motile cilia, necessary for the regulation of ciliary coordinated beating. Polyglutamylates non-tubulin protein nucleotidyltransferase CGAS, leading to CGAS DNA-binding inhibition, thereby preventing antiviral defense response.
Synonyms: TTL.6; FLJ35808
Tractability: No criterion of Open Targets' tractability assessment is met for any kind of drug.
Gene: Protein-coding gene on chromosome 17 (48,762,234 to 48,817,229, reverse strand). Ensembl gene ENSG00000170703.
Subcellular location: Cytoplasm; Cytoplasm, cytoskeleton; Cytoplasm, cytoskeleton, cilium axoneme; Cytoplasm, cytoskeleton, cilium basal body
Subcellular location (Human Protein Atlas): Basal body; Flagellar centriole; Microtubules; Primary cilium; End piece; Mid piece; Principal piece
Pathways (Reactome):
Metabolism of proteins: Carboxyterminal post-translational modifications of tubulin
Gene Ontology:
Molecular function: protein binding; protein-glutamic acid ligase activity; protein-glutamic acid ligase activity, elongating; protein-glutamic acid ligase activity, initiating; tubulin binding; tubulin-glutamic acid ligase activity
Biological process: microtubule bundle formation; protein polyglutamylation; regulation of cilium beat frequency involved in ciliary motility
Cellular component: ciliary basal body; cilium; microtubule cytoskeleton; cytoplasm; cytosol; 9+0 non-motile cilium; axoneme; cytoskeleton
Genetic constraint (gnomAD): Loss-of-function variants: 71 observed, 98.68 expected, observed/expected ratio (o/e) 0.72, 90% interval 0.59 to 0.88. The upper end of that interval is the gene's LOEUF score, 0.88, which puts it in group 3 of 6, group 1 being the genes least tolerant of losing a copy. Missense variants: 1,025 observed, 1,133.7 expected, observed/expected ratio (o/e) 0.9, 90% interval 0.86 to 0.95. Synonymous variants: 411 observed, 439 expected, observed/expected ratio (o/e) 0.94, 90% interval 0.86 to 1.02.
Homologues: Orthologues: chimpanzee TTLL6 (98% identical), macaque TTLL6 (92% identical), dog TTLL6 (73% identical), rabbit TTLL6 (66% identical), pig TTLL6 (64% identical), mouse Ttll6 (62% identical), guinea pig TTLL6 (59% identical), rat Ttll6 (53% identical), Drosophila melanogaster TTLL3A (11% identical), Caenorhabditis elegans ttll-15 (10% identical), Drosophila melanogaster TTLL15 (10% identical), Drosophila melanogaster TTLL3B (9% identical). Paralogues in human: TTLL13 (37% identical), TTLL7 (28% identical), TTLL4 (20% identical), TTLL11 (18% identical), TTLL2 (15% identical), TTLL1 (14% identical), TTLL9 (13% identical), TTLL3 (13% identical), TTLL10 (12% identical), TTLL8 (12% identical), TTLL12 (10% identical), KPRP (8% identical).
Diseases named in the same sentence as TTLL6 in open-access papers:
TTLL6 is named in the same sentence as 10 diseases in open-access papers, as found by Europe PMC text mining. Sharing a sentence is not in itself a finding about the gene and the disease. The quoted sentences say what the papers report.
esophageal cancer (1 paper, 2020). A primary or metastatic malignant neoplasm involving the esophagus. "Although the biological functions of TTLL6 in esophageal cancer require further study, our data provided first inspection of TTLL6 deficiency induced CDPP resistance and provided an intervention strategy for drug resistance reversal of esophageal cancer chemotherapy." (PMID 33123270, 2020). "Therefore, TTLL6 may paly critical roles in the development of MDR and may be a potential candidate for drug resistant esophageal carcinoma therapy." (PMID 33123270, 2020).
tauopathies (1 paper, 2015). "Here we review the findings supporting a role for Tau, spastin and TTLL6 in AD and other tauopathies, HSP and neurodegeneration, and summarize possible therapeutic approaches for AD and HSP." (PMID 26691836, 2015).
infection (1 paper, 2020). The state of being infected such as from the introduction of a foreign agent such as serum, vaccine, antigenic substance or organism. "To further investigate the role of TTLL6 in the resistance of chemotherapy, we first selected TTLL6 stable knockdown cells (EC109/CDDP-shRNA/TTLL6) by lentiviral infection, and EC109/CDDP-shRNA/control cells were served as control." (PMID 33123270, 2020).
tumor (1 paper, 2020). "The average reduced rate of tumor volume was significantly lower in TTLL6 overexpressed group than that in GFP overexpressed control group, and it was significantly higher in TTLL6 silenced group than that in shRNA control group." (PMID 33123270, 2020). "Furthermore, animal model confirmed that TTLL6 negatively regulated the growth of xenograft tumor after chemotherapy." (PMID 33123270, 2020).
TTLL6 also shares sentences with these, for which no sentence is quoted: Blindness (1 paper); cone/cone-rod dystrophies (1); Joubert syndrome (1); meningioma (1); Parkinson disease (1); retinitis pigmentosa (1).